NPC2 (NPC intracellular cholesterol transporter 2)
Diseases named in the same sentence as NPC2 in open-access papers (continued):
Sharing a sentence is not in itself a finding about the gene and the disease.
neuropathy (1 paper, 2011). A disorder affecting the nervous system that manifests with pain, tingling, numbness, and/or muscle weakness. "Most striking are data demonstrating that the lipid chelator 2-hydroxypropyl-β-cyclodextrin (CD) partially can replace the function of NPC1 and NPC2 proteins, diminishes neuropathy, delays motor deficits, and increase median survival in both NPC1−/− and NPC2−/− mice." (PMID 22073306, 2011).
non-small cell lung carcinoma (1 paper, 2013). A group of at least three distinct histological types of lung cancer, including non-small cell squamous cell carcinoma, adenocarcinoma, and large cell carcinoma. "Out of 44 matched non-small cell lung carcinoma pairs, 30 tumor tissue samples (68%) had greater NPC2 expression than their normal counterparts (p=0.02)." (PMID 24147030, 2013).
oligoasthenoteratozoospermia (1 paper, 2024). A form of male infertility that is characterized by a combination of low number or oligozoospermia, poor motility or asthenozoospermia, and abnormal shape or teratozoospermia of sperms. "Key proteins associated with sperm function, such as NPC intracellular cholesterol transporter 2 (NPC2), galectin-3-binding protein (LGALS3BP), lipocalin-1 (LCN1), and prolactin-inducible protein (PIP), show reduced expression in oligoasthenoteratozoospermia (OAT)." (PMID 39685846, 2024).
papillary carcinomas of breast (1 paper, 2011). "In addition, choroid plexus of the brain, colon polyps, and papillary carcinomas of breast expressed NPC2 protein (not shown here)." (PMID 21253586, 2011).
papillary thyroid carcinoma (1 paper, 2011). "Upregulation of NPC2 in human papillary thyroid cancer and significant decrease in cell proliferation in NPC2-depleted H460 cells suggest that NPC2 protein may also control cell proliferation in papillary tumors." (PMID 21253586, 2011).
prostate carcinoma (1 paper, 2014). A carcinoma that arises from epithelial cells of the prostate gland. "Therefore, further studies on the association of DEPTOR and NPC2 with prostate cancer are needed." (PMID 24800880, 2014).
pulmonary alveolar proteinosis (1 paper, 2013). A rare lung disorder characterized by the filling of the pulmonary alveoli with proteinaceous material which stains positive with periodic acid-Schiff stain. "NPC2 hypomorph mice and patients with NPC2 disease develop alveolar periodic acid-Schiff-positive material, indicative of pulmonary alveolar proteinosis (PAP)." (PMID 23843985, 2013).
pulmonary fibrosis (1 paper, 2011). Chronic progressive interstitial lung disorder characterized by the replacement of the lung tissue by connective tissue, leading to progressive dyspnea, respiratory failure, or right heart failure. "Intriguingly, autopsy has revealed that NPC2 deficiency is associated with pronounced pulmonary fibrosis, known to be primarily mediated by activated fibroblasts." (PMID 22073306, 2011).
renal cell carcinoma (1 paper, 2013). "Nevertheless, the functional relevance of NPC2 in renal cell carcinoma remains unclear and further studies are needed to elucidate the role of NPC2 in kidney, both physiologically and pathologically." (PMID 24147030, 2013).
renal dysfunction (1 paper, 2021). "Correlation analysis revealed that plasma NPC2 had the strongest association with renal dysfunction (rs = 0.36), followed by the overall level of organ dysfunction (SOFA_sum, rs = 0.32), and dysfunctions of heart and coagulation (rs = 0.2)." (PMID 33723331, 2021). "Coagulation parameters, such as the plateletcrit, platelet count, SOFA_coagulation and fibrinogen degradation product, exhibited highest correlation coefficients with NPC2 concentration, followed by renal dysfunction indicators, such as creatinine and urea nitrogen." (PMID 33723331, 2021).
sarcoidosis (1 paper, 2021). Sarcoidosis is a multisystemic disorder of unknown cause characterized by the formation of immune granulomas in involved organs. "In fact, TB induced the highest median NPC2 blood levels (0.58, 95% CI 0.37–0.80), which was followed by active sarcoidosis (0.46, 95% CI 0.23–0.71)." (PMID 34685683, 2021).
steatosis (1 paper, 2018). Increased lipid within the cytoplasm of cells. "Neither NPC2 treatment regimen affected the degree of steatosis or ballooning when comparing with HFHC fed controls." (PMID 29522534, 2018).
tauopathies (1 paper, 2024). "Thus, pathogenic NPC1 and NPC2 mutations are the causative agents for NPC but do not represent a general risk factor for other tauopathies." (PMID 38554150, 2024).
varicocele (1 paper, 2015). A condition characterized by the dilated tortuous veins of the spermatic cord with a marked left-sided predominance. "Our data indicates that NPC2 was overexpressed with medium abundance in the unilateral varicocele group suggesting alterations in membrane fluidity, capacitation and acrosome reaction in these patients." (PMID 25890347, 2015).
vitamin A deficiency (1 paper, 2021). Deficiency of vitamin A due to malnutrition, malabsorption, or dietary lack. "On the other hand, considering that all-trans retinoic acid (ATRA) triggers an NPC2-dependent antimicrobial response against Mtb, it is important to investigate whether vitamin A deficiency could contribute to false-negative results in individuals otherwise expected to have an NPC2high pattern." (PMID 34685683, 2021).
tumor (28 papers, 2011 to 2026). "Our findings indicated that, surprisingly, NPC2 expression was substantially associated with tumor stage in LIHC (p value = 0.00575)." (PMID 39690926, 2024). "Comparative analysis showed that NPC2 was upregulated in 11 tumor types, while NUSAP1 was upregulated in as many as 22 tumor types." (PMID 40393971, 2025). "Lastly, we confirmed the high expression of NPC2 in tumor tissue macrophages using immunofluorescence." (PMID 40620715, 2025). "Through external validation using GSE268238, we confirmed that NPC2 was highly expressed in macrophages from tumor tissues." (PMID 40620715, 2025). "Cell communication analysis revealed increased interaction in tumor tissues, especially involving NPC2, LY96, and TPP1 positive macrophages, which facilitated tumorigenesis and immune evasion." (PMID 40620715, 2025). "Patients with NPC2 downregulation express higher alpha-fetoprotein, a wide range of tumor types, vascular infiltration, later pathological stage, and lower survival." (PMID 40302802, 2025). "The age, stage, radiation therapy, residual tumor, and NPC2 expression showed independent prognostic value for OS." (PMID 38001127, 2023). "The expressions of NPC1L1 and NPC2 in HCC tumor tissues were often lower than those in peritumor tissues, according to the patterns of expression in tumor and peritumor tissues." (PMID 36034854, 2022). "According to previous reports, NPC2 is considered to be closely related to lipid metabolism and tumor metastasis." (PMID 36249779, 2022). "Immunohistochemical staining was performed to visualise the expression of BMP1, CD109, LTBP1, PSAP, and NPC2 in human control colonic tissue, primary tumour, and liver metastasis." (PMID 36134447, 2022). "In the primary tumour, NPC2 showed preferential membrane staining of the tumour, being more cytoplasmic in the metastasis." (PMID 36134447, 2022). "In this research, we found that NPC2 was negatively correlated with tumor purity and then were functionally investigated in tumor infiltrating immune cells." (PMID 33777094, 2021). "What’s more, the correlation among NPC2 expression and tumor infiltrating B cell, CD8 + T cell, macrophages, neutrophils, and dendritic cells in GBM cancer samples was also obvious." (PMID 33777094, 2021). "Then, we analyzed the correlation of NPC2 expression with tumor purity and tumor infiltrating immune cells." (PMID 33777094, 2021). "Studies on isolated cells ex vivo confirm that NPC2 is secreted from tumour cells and is taken up by IMCs wherein it suppresses secretion of the CCR1 ligand CC chemokine 6 (CCL6), at least in part by facilitating its lysosomal degradation." (PMID 26183450, 2015). "We also measured tumour burden of Npc2+/+ and Npc2+/hypo BVE lung by tumour area quantification using histological sections, leading to the same conclusion." (PMID 26183450, 2015). "Among 50 matched liver tumor tissue and tumor-adjacent tissue pairs, 36 tumor tissue samples (72%) showed much lower NPC2 expression than their tumor-adjacent tissue sample (p=0.02)." (PMID 24147030, 2013). "Among 33 patients, 18 (54.5%) tumor tissue samples had a much higher NPC2 expression than the equivalent normal tissue sample (p=0.002)." (PMID 24147030, 2013). "In this study, we generated and characterized a number of NPC2 mAbs and then assessed their immunoreactivity using multiple tumor tissue arrays." (PMID 24147030, 2013). "Using the TCGA and GTEx data, we could learn the expression of five genes of the TEXPM construct, FTL, GZMA, CD14, and NPC2 were highly expressed in tumor tissues, and IER3 was highly expressed in paracancerous tissues." (PMID 37354485, 2023). "We noted that additional altered genes encode structural proteins such as membrane channels (e.g., APQ3) and transporters (e.g., SLC34A2 and NPC2) that may be coupled to key regulators in tumor cells." (PMID 33144684, 2021). "As expected, significant positive correlation of NPC2 expression with tumor purity was shown." (PMID 33777094, 2021).
tumor (continued). "Furthermore, in a screen for proteins secreted from V600EBRAF-expressing premalignant tumour cells, we identified the cholesterol-binding protein Niemann-Pick type C2 (NPC2)." (PMID 26183450, 2015). "Thus, NPC2 secreted by pre-malignant lung tumours interferes with the tumour microenvironment through paracrine mechanisms." (PMID 26183450, 2015). "Since our data suggest that NPC2 could potentially be a tumour suppressor that functions at pre-malignant stages, quantitative evaluation of NPC2 secretion by lung tumours at different developmental stages will be important." (PMID 26183450, 2015). "Interestingly, at this time point, Mac2+ IMCs on the Npc2+/hypo background were often found co-located with a limited number of Ki67+ tumour cells within tumour interstices that had largely lost Ki67 positivity (Fig6F)." (PMID 26183450, 2015). "Therefore, the discrepancy of papillae formation between xenograft experiments (tumor of NPC2 depleted cells under the skin) and live animal model (born with NPC2 defect) exists." (PMID 21253586, 2011). "Data from TCGA were used to explore the expression differences of NPC2, LY96, and TPP1 at the overall tumor level." (PMID 40620715, 2025). "NPC2 positive macrophages secrete TNF and TGFB1 that act on tumor cells, thereby enhancing the proliferation of tumor cells." (PMID 40620715, 2025). "Like NPC2, LY96 positive macrophages secrete MIF affecting T cells, inhibiting T cell activity, and mediating tumor immune escape." (PMID 40620715, 2025). "The result indicated that the expression levels of NPC2 and ITGAV are related to GICs prognosis and tumor—immune signature." (PMID 39690926, 2024). "Following the overexpression of KCNE1, NPC2, and SFTPD, M0 macrophages exhibited a substantial reduction in the polarization of M2 macrophages as well as the quantity of tumor-promoting cytokines that were produced by the cells." (PMID 38509982, 2024). "For the immunologic significance, NPC2 and ITGAV were positively correlated with the abundance of tumor‐infiltrating lymphocytes and macrophages." (PMID 39690926, 2024). "Similarly, NPC2 positive macrophages secrete MIF acting on T cells, inhibiting T cell activity and mediating tumor immune escape." (PMID 40620715, 2025). "NPC2, LY96, and TPP1, highly expressed in TAMs, were implicated in promoting tumor growth and immune escape, offering potential targets for novel therapeutic interventions." (PMID 40620715, 2025). "Indeed, the categorization of macrophages according to NPC2, LY96, and TPP1 expression highlighted their differential impact on the tumor microenvironment." (PMID 40620715, 2025). "Ultimately, we found that NPC2, LY96, and TPP1 are highly expressed in tumor tissues." (PMID 40620715, 2025). "Genes involved in glycolysis (ALDOA, LDHA, PGK1, PFKL, PGM1) and other metabolic processes (GPX4, PRDX4, ACO2, ASPH, IDH2, SQLE, NPC2, SPTSSA) were upregulated in primary tumor cells, suggesting that the metabolism in primary tumors was distinct from that in their matched metastasis." (PMID 39225101, 2024). "Finally, we characterized the expression of three LSAGs (KCNE1, NPC2, and SFTPD) in malignant lung epithelium and assessed their impact on tumor malignancy related phenotypes." (PMID 38509982, 2024). "In addition, to further verify the protein level of NPC2 and ITGAV expression, we compared the IHC results from the HPA database; and we found that the NPC2 and ITGAV proteins were expressed higher in tumor tissues than the normal ones." (PMID 39690926, 2024). "Furthermore, as the significant correlation in tumor infiltrating cell except CD4 + cell, correlation of B cell, T cell CD8+, M1 and M2 macrophages, neutrophil cells, and dendritic cells markers with NPC2 expression were analyzed." (PMID 33777094, 2021).
tumor (continued). "To better understand the contribution of these GBM cell-states within our Q-Cell resource, we firstly analysed 257 unique genes, separating tumours into six metamodules (MES1-, MES2-, NPC1-, NPC2-, OPC-, and AC-like) as per Suva and colleagues encompassing each of the identified four cell-states." (PMID 31973233, 2020). "Therefore, to further culture H1299 cells with HCC827 and M0 macrophages, we found that after over-expression of KCNE1, NPC2, SFTPD, M0 macrophage polarization significantly decreased, and the amount of tumor-promoting cytokines secreted by cells was significantly reduced." (PMID 38509982, 2024). "However, the Npc2+/hypo BVE mice demonstrate IMC amplification by ∼2- to 6-fold without significant enhancement of tumour progression or AT2 growth (Fig6)." (PMID 26183450, 2015). "Neither AT2 cell number nor their ability to incorporate BrdU was altered in Npc2+/hypo BVE mice at the pre-senescent stage of tumour development (5 weeks p.p.), demonstrating that NPC2 does not regulate the intrinsic growth of the pre-malignant tumour cells, at least at the pre-senescent stage." (PMID 26183450, 2015). "NPC2 showed a relatively higher expression in GBM samples, and a negative correlation with tumor purity and tumor infiltrating immune cells." (PMID 33777094, 2021).
cancer (18 papers, 2011 to 2025). A tumor composed of atypical neoplastic, often pleomorphic cells that invade other tissues. "NPC2 is associated with lipid metabolism and the innate immune system, and it influences the formation and progression of various types of cancer cells, playing critical regulatory functions." (PMID 38001127, 2023). "The proteomic signature detected in blood plasma of the NPC2-deficient mice was associated with cancer." (PMID 34050187, 2021). "Our results extend these findings and suggest that mice with NPC2 deficiency express a cancer-related protein profile in blood plasma." (PMID 34050187, 2021). "Taken together, these results indicated that aberrant expression of NPC2 is associated with different cancers and that the change in expression may be either up or down depending on the tissue." (PMID 24147030, 2013). "The list was narrowed down to the two candidate genes, which shared the maximum overlap between the cancer types, including NPC2 and ITGAV." (PMID 39690926, 2024). "In recent years, increasing evidence has revealed the important role of NPC2 in the development and progression of various human cancers, including gastric cancer." (PMID 38001127, 2023). "Confirming previous studies that associated NPC2 levels with various cancers as measured directly by ELISA85, our results associated the blood plasma protein signature of NPC2 deficiency to cancer." (PMID 34050187, 2021). "In comparison to ciliated, Club/Clara cells, pulmonary alveolar type 1 (AT1) and pulmonary alveolar type 2 (AT2), the EGFRex19 cancer cell cluster was characterized by high expression of NPC2 and surfactant genes SFTPB, SFTPC, and SFTPD." (PMID 33712615, 2021). "While NPC2 is mainly associated with metabolism and NPC disease, disease ORAs resulted in multiple cancer associations." (PMID 34050187, 2021). "Modulation of cholesterol homeostasis by NPC2 also affects activation of mammalian target of rapamycin (mTOR), a critical signaling cascade in several types of cancer including HCC." (PMID 26020769, 2015). "Our findings indicated that our NPC2 monoclonal antibody has potentially useful applications in the areas of clinical diagnosis and cancer progression across multiple tissues." (PMID 24147030, 2013). "In order to investigate the clinical application of NPC2 mAb, we detected the expression of NPC2 in various normal and cancer tissues using IHC staining." (PMID 24147030, 2013). "When compared to their normal tissue equivalents, NPC2 overexpression was observed in cancers of the breast, colon and lung." (PMID 24147030, 2013). "After screening several cancer cell lines, we found wild H460 cell line that constitutively expressed abundant NPC2 protein." (PMID 21253586, 2011). "These NPC2 or ITGAV‐related genes all play a role in various cancers." (PMID 39690926, 2024). "Further validation of these results is needed and may shed light on the less understood role of NPC2 in cancer." (PMID 34050187, 2021). "The role of Niemann-Pick Type C2 (NPC2) protein in cancer is just beginning to be understood." (PMID 26020769, 2015). "However, the roles of NPC2 expression in human cancers are not fully understood notwithstanding its known role in cholesterol binding." (PMID 24147030, 2013). "In this study, we have pinpointed the impact of various different cancers on NPC2 expression." (PMID 24147030, 2013). "However, little is known about the significance of NPC2 in cancer." (PMID 24147030, 2013). "Since NPC2 negatively regulates ERK1/2 mitogen activated protein kinase (MAPK) phosphorylation in fibroblast cells, a disturbance in NPC2 expression may be associated with important human diseases including cancer." (PMID 24147030, 2013). "These suggest that these five cholesterol-related genes (APOA1, APOC3, ABCA1, NPC2, CD36) play an important role in cancer." (PMID 40302802, 2025). "We conduct an in‐depth investigation of how NPC2 and ITGAV are expressed in human cancers and adjacent normal tissues." (PMID 39690926, 2024).
cancer (continued). "We evaluated the Human Protein Atlas dataset and identified NPC Intracellular Cholesterol Transporter 2 (NPC2) and Integrin Subunit Alpha V (ITGAV) as probable poor predictive genes for these cancers." (PMID 39690926, 2024). "Following this, we investigated the mRNA expression levels of NPC2 and ITGAV in 33 human cancers and matched normal tissues and healthy individuals." (PMID 39690926, 2024). "Through starBase (an online tool), NPC2, LRRC8A and NUCB2 were predicted with the strict condition (pan-cancer ≥ 8; degradome data ≥ 3 and clip data ≥ 5)." (PMID 32226311, 2020). "In total, we obtained 55 target genes in NPC1, 1, 241 target genes in NPC2, 35 target genes in NPC3 and 251 target genes in non-cancer group by searching the miRWalk 2.0 database." (PMID 29455649, 2018). "Finally, NPC2 and ITGAV's molecular pathways in cancer are complex and need to be validated in fully independent research before being implemented in clinical practice." (PMID 39690926, 2024). "However, the expressions of NPC2 in human cancers have not been explored in detail." (PMID 24147030, 2013).